CDK4 (cyclin dependent kinase 4)
Diseases named in the same sentence as CDK4 in open-access papers (continued):
Sharing a sentence is not in itself a finding about the gene and the disease.
breast cancer (continued). "We compared two breast cancer cell lines, the T47D and KPL1 models, the latter reported to be less responsive to CDK4/6i." (PMID 36446794, 2022). "Preliminary results from the NM cohort of patients receiving abemaciclib, a cyclin-dependent kinase 4/6 (CDK 4/6) inhibitor, in breast cancer revealed a PFS of 5.9 months and an OS of 8.4 months." (PMID 36612116, 2022). "Several previous reports have shown that treatment of breast cancer cell lines with FGFR inhibitors downregulates CCND1 and CCND2 expression and inhibits CCND/CDK4 activity, resulting in decreased pRB phosphorylation." (PMID 35884537, 2022). "Chemotherapy and radiotherapy are important adjuvant treatments for breast cancer patients, and new treatment strategies targeting HER-2, CDK4/6, ER, or aromatase have appeared in recent years." (PMID 35402243, 2022). "In xenogaft models of breast cancer, depletion of CDK2 and CDK4/6 has reduced tumor growth and palbociclib resistance." (PMID 36266723, 2022). "To test if such synergy exists in the context of ESR1 mutant breast cancer, we tested OTX015 in combination with abemaciclib, an approved CDK4/6 inhibitor, in MCF-7 Y537S cells." (PMID 35881485, 2022). "It has been shown that miR-6775-3p can negatively regulate CDK4, CDK6, MMP17, and MMP24 levels in breast cancer cells by binding to the 3′UTR of their mRNAs, thereby inhibiting the proliferation, migration, and invasive abilities of breast cancer cells." (PMID 35891968, 2022). "Recently, clinical trials on the addition of a CDK4/6 inhibitor to the combination of fulvestrant and HER2-targeted therapy have been conducted in patients with HR + HER2+ breast cancer." (PMID 34983437, 2022). "In MONALEESA 2-, 3-, and 7-trials, the largest biomarker analysis of any CDK4/6 inhibitor in advanced breast cancer, blood samples from 1507 ER+ HER2-metastatic breast cancer patients were analyzed at baseline using NGS with a targeted panel of 557 genes." (PMID 35565189, 2022). "Palbociclib, a selective inhibitor of CDK4/6, has been FDA-approved for the treatment of breast cancer and has been shown in multiple studies to be effective in the treatment of HCC." (PMID 36347033, 2022). "In the breast cancer cell line MDA-MB-453, intracellular CDK4 activity was functionally inhibited during the treatment phase, as observed by the complete depletion of pRb (Ser780) regardless of treatment." (PMID 35813283, 2022). "Since 2015, three CDK4/6 inhibitors, palbociclib, ribociclib, and abemaciclib have been approved for HR‐positive/HER2‐negative breast cancer in various settings and combination regimens." (PMID 36254250, 2022). "To date, CDK4/6 inhibitors have been approved for the treatment of advanced HR+/HER2− breast cancer, whereas TNBC tumors are relatively resistant to CDK4/6 inhibitors." (PMID 35449080, 2022). "We found that decreased expression of circ_6014 decreased the protein expression levels of PCNA, CDK2/CCNE1, and CDK4/6/CCND1, and overexpression of circ_6014 increased the expression of these proteins in breast cancer cells (Student’s t test, p < 0.05)." (PMID 35383130, 2022). "Isoangustone A dose-dependently decreased DNA synthesis and induced G1 phase arrest in human prostate and mouse breast cancer cells, reduced the levels of CDK2 and CDK4 as well as cyclin A and cyclin D1 proteins, and also induced a decrease in CDK2 activity." (PMID 36278690, 2022). "As an example, cyclin-dependent kinase 4/6 (CDK4/6) inhibitors including palbociclib, abemaciclib and ribociclib are well established therapies in combination with endocrine therapy in breast cancer." (PMID 35158978, 2022). "The efficacy and safety of the combination of endocrine therapy (ET) and CDK4/6 inhibitors for patients with hormone receptor (HR)-positive HER2-negative metastatic breast cancer (BC) presenting with visceral crisis or life-threatening conditions represent a challenge for daily clinical practice." (PMID 34692469, 2021).
breast cancer (continued). "Although CDK4/6 inhibitors are an established treatment for hormone receptor–positive, HER2-negative metastatic breast cancers, their benefit in other malignancies remains limited." (PMID 33427211, 2021). "Taken together, our data suggest that HR+ breast cancer cell lines with elevated FGFR1 levels (either because of amplification or increased mRNA levels) require the combination of ER, CDK4/6 and FGFR1 blockade for maximum cell cycle arrest." (PMID 33579347, 2021). "Phase III trials have demonstrated that CDK4/6 inhibitors offer prolonged progression-free (PFS) and overall survival (OS) in patients with metastatic HR-positive, HER2-negative breast cancer compared with endocrine therapy." (PMID 34198899, 2021). "The recent addition of cyclin-dependent kinase 4 (CDK4) and CDK6 inhibitors (palbociclib, ribociclib, abemaciclib) to endocrine therapy have remarkably improved the outcome of patients with HR+ advanced breast cancer." (PMID 33477469, 2021). "For now, three CDK4/6 inhibitors (palbociclib, ribociclib, and abemaciclib) received FDA approval for the treatment of HR-positive or HER2-negative breast cancer." (PMID 34778045, 2021). "Combined miR-126 transfection and CDK4/6 inhibitor ribociclib application resulted in a greater antitumor effect than either agent alone in luminal and HER2-positive breast cancer cell lines (p < 0.005)." (PMID 34439268, 2021). "Palbociclib is the first CDK4/6 inhibitor received FDA approval for HR+, HER2– breast cancer treatment in 2015 whereas abemaciclib is the third approved CDK4/6 inhibitor (approved in 2018)." (PMID 34735543, 2021). "The CDK4/6 inhibitors palbociclib, ribociclib, and abemaciclib have been recently approved by the Food and Drug Administration (FDA) for the treatment of breast cancer." (PMID 34067359, 2021). "This has led to the development of CDK4/6 inhibitors (palbociclib, ribociclib, and abemaciclib), which have been approved by the FDA for the treatment of estrogen receptor (ER)-positive breast cancer." (PMID 33686962, 2021). "Our results also established that inhibition of CK1ε protects hypo-phosphorylated RB1 from degradation and simultaneously abolishes CDK4/6i-induced CDK6 accumulation, thereby providing a potential therapeutic strategy for breast cancer patients." (PMID 34508104, 2021). "The inhibitor of cyclin-dependent kinases 4 (CDK4), which has already been approved by the Food and Drug Administration (FDA) for the treatment of breast cancer, markedly repressed the proliferation of Tregs." (PMID 34489925, 2021). "CDK4/6 and PI3K inhibitors together have been shown to induce breast cancer cell apoptosis in vitro and suppress tumor growth in patient-derived tumor xenograft models." (PMID 33790792, 2021). "Our findings are fortified by recently published studies describing the synergistic effect of CDK4/6 inhibitor Palbociclib and the PARP inhibitors Olaparib or Niraparib against breast cancer cells." (PMID 33923231, 2021). "A recent study conducted on ER+ advanced breast cancer patients treated with a combination of the CDK4/6 inhibitor ribociclib and letrozole showed that loss of PTEN expression due to AKT activation could lead to the development of resistance to CDK4/6 inhibition." (PMID 34706703, 2021). "CDK4/6 inhibitors (CDK4/6i) have shown impressive improvement of PFS and OS in ER+ advanced breast cancer in combination with either aromatase inhibitors or fulvestrant, and these combinations have recently become standard-of-care in this patient population." (PMID 33398005, 2021). "We examined the effects of the CDK4/6 inhibitor abemaciclib and ABT‐263 on two human breast cancer cell lines." (PMID 34761877, 2021). "In conclusion, abemaciclib, a CDK4/6 inhibitor, and ABT‐263/ABT‐737 have therapeutic potential for breast cancer." (PMID 34761877, 2021).
breast cancer (continued). "Three CDK4/6 inhibitors (palbociclib, ribociclib, abemaciclib) are FDA-approved to treat advanced-stage or metastatic, hormone-receptor-positive, HER2-negative breast cancer (BC)." (PMID 33161487, 2021). "In keeping with the observed reduction of RB1 protein abundance, immunostaining analysis also showed decreased RB1 signals in the presence of CDK4/6i in MCF7 and MDA-MB-231 breast cancer cells." (PMID 34508104, 2021). "Due to according references with synergistic efficacy of a combined inhibition of PI3K and CDK4/CDK6, e.g. in breast cancer models, manual curation suggested PI3K-inhibition in combination with palbociclib in case of PIK3CA mutation." (PMID 33712636, 2021). "We found that CDK4/6i alone reduced MCM3 levels in both endocrine-sensitive (MCF7/S0.5) and -resistant (TamR-1, LetR-1, and FulvR-1) breast cancer cell lines." (PMID 33398005, 2021). "Even still, the combination of CDK4/6 and HER2 inhibitors is met with the development of drug resistance in HER2-positive breast cancer treatment." (PMID 34208071, 2021). "In this review, our perspective is that PI3K/AKT/mTOR pathway activation is related to conventional therapy resistance in breast cancer, including endocrine therapy, HER2-targeted therapy, CDK4/6 and PARP inhibitors, chemotherapy and immunotherapy." (PMID 33790792, 2021). "To date, CDK inhibitor therapy, specifically inhibitors targeting CDK4 and CDK6, has found the most success in the treatment of HR+ breast cancer." (PMID 34771508, 2021). "CDK4/6 inhibitors have had a great deal of success in treating hormone receptor-positive (HR+) and HER2- advanced breast cancer patients." (PMID 34729098, 2021). "The breast cancer subnetwork is found to contain (i) valid biomarkers including PIK3CA, PTEN, BRCA1, AR and EGFR; (ii) validated drug targets TOP2A, CDK4, HDAC1, IL6, BRCA1, HSP90AA1 and AR; (iii) synergistic drug targets EGFR and BIRC5." (PMID 35053185, 2021). "Palbociclib, an inhibitor of CDK4 and CDK6, was approved by the FDA in 2015 for the treatment of breast cancer." (PMID 34211613, 2021). "In accordance with the proposed mechanism for how MDM2 can induce breast cancer resistance to CDK4/6 inhibitors, preclinical studies have evaluated the effects of MDM2 inhibitors on the growth of CDK4/6-resistant tumors." (PMID 34830174, 2021). "The MONARCH-2 and MONARCH-3 studies examined a third CDK4/6 inhibitor, abemaciclib, in the context of HR+, HER2− breast cancer." (PMID 34771508, 2021). "Three CDK4/6 inhibitors (CDK4/6is) Palbociclib, Ribociclib (LEE011) and Abemaciclib have been used in a variety of clinical trials in breast cancer." (PMID 34138895, 2021). "In another study, it was reported that treatment of MCF-7 breast cancer cell line with 1,25(OH)2D3 induces cell cycle arrest at G0/G1phase via inhibition of CDK2 and CDK4 56-60." (PMID 34421361, 2021). "In particular, CDK4/6 inhibitors palbociclib, ribociclib and abemaciclib have shown efficacy in in vitro models of EAC and promising results in breast cancer, non-small cell lung cancer and melanoma patients." (PMID 34298611, 2021). "First, we developed in vitro models of acquired resistance to two different CDK4/6 inhibitors, palbociclib (PAL) and abemaciclib (ABE), using two different HR-positive HER2-negative breast cancer cell lines." (PMID 32860163, 2021). "FDA has approved CDK4/6 inhibitors in HER2-negative, ER-positive postmenopausal breast cancer patients, which can block the binding site of cell cycle protein D1 on CDK4/6 thereby inhibiting tumor cell proliferation." (PMID 34869005, 2021). "Targeting Cyclin-dependent Kinase 4 (CDK4) and Cyclin-dependent Kinase 6 (CDK6) in ER+ breast cancer is useful because these cancers often have the cyclin D1–CDK4/6–Rb pathway activated." (PMID 34830174, 2021).
breast cancer (continued). "The expanding clinical application of CDK4- and CDK6-inhibiting drugs in the managements of breast cancer has raised a great interest in testing these drugs in other neoplasms." (PMID 34445095, 2021). "Oral highly selective inhibitors of CDK4 and CDK6, such as abemaciclib, represent an important therapeutic advancement in HR+ breast cancer." (PMID 35223458, 2021). "By combining abemaciclib with a PI3K inhibitor, three pathways (Akt, PIM, and CDK4) to mTOR activation are neutralized, suggesting a potential combination strategy for the treatment of PIK3CA-mutant ER+ breast cancer." (PMID 32391118, 2020). "In breast cancer, the induction of HO-1 and its catalyzed byproduct, CO, by CUR can attenuate heat shock protein (HSP) 90 activity and its client proteins Akt, CDK4, and cyclinD1 to further suppress the invasion and proliferation of cells." (PMID 32188144, 2020). "Three third-generation CDK inhibitors, palbociclib, ribociclib, and abemaciclib, have higher specificity to CDK4/6 than other members of the CDK family and have been translated into clinical use against advanced luminal breast cancer." (PMID 33364954, 2020). "Apart from non-selective agents that block CDKs, small molecular weight inhibitors with dual specificity for the close homologues CDK4 and CDK6 have been FDA approved for the treatment of breast cancer." (PMID 33255177, 2020). "Although the cdk4/6 gene expression level in breast cancer is relatively low, a marked antitumor effect of CDK4/6 inhibitors has been observed in breast cancer, so we speculate that it may also work in other malignancies, especially in those cancers with high cdk4/6-related gene expression." (PMID 32357912, 2020). "This article summarizes the current knowledge (published studies accessed through PUBMED) on drugs used in chemotherapy, hormone therapy, anti-HER2 drugs, CDK4/6 inhibitors, PARP inhibitors, and immune therapy in breast cancer patients undergoing dialysis." (PMID 32508921, 2020). "Among them, targeted therapy, such as trastuzumab, CDK4/6 inhibitors, and PI3K/Akt/mTOR inhibitors, significantly prolongs the survival time of patients with breast cancer." (PMID 32518527, 2020). "Accordingly, drug development programs have yielded three dual CDK4/6 inhibitors (abemaciclib, palbociclib, and ribociclib) that have been FDA-approved for treatment of breast cancer." (PMID 32488087, 2020). "In breast cancer, luminal and basal breast cancer forms were determined using PAM50, and as expected the luminal form of the disease expressed lower levels of the CDK4/6-RB integrated signature." (PMID 32242058, 2020). "In contrast, miR-486 inhibits cell proliferation and invasion through repressing GAB2, PIK3R1, Snail, neuropilin-2, CDK4, or PIM-1 in non-small-cell lung cancer, colorectal cancer, prostate cancer, hepatocellular carcinoma, and breast cancer cells." (PMID 32155804, 2020). "Combined targeting of CDK4/6 and ER is now the standard of care for patients with advanced ER+/HER2− breast cancer." (PMID 32795346, 2020). "Ribociclib (RIB, LE011, Kisqali®), an orally administered inhibitor of cyclin-dependent kinase-4/6 (CDK-4/6) complex, is clinically effective for the treatment of several malignancies, including advanced breast cancer." (PMID 33138174, 2020). "CDK4/6 inhibitors (CDK4/6i) are recommended in patients with estrogen receptor (ER)-positive, HER2-negative advanced breast cancer (ABC)." (PMID 32784518, 2020). "Palbociclib, a cyclin-dependent kinase 4/6 (CDK4/6) inhibitor, has been used to treat patients with ER+ and HER2− advanced breast cancer." (PMID 33014829, 2020). "Palbociclib can inhibit the expression of cyclin-dependent kinase 4 (CDK4) and reduce the proportion of estrogen-induced CSCs in ER+ and HER2− breast cancer cell lines." (PMID 33014829, 2020). "Palbociclib is the first FDA-approved CDK4/6 inhibitor for the treatment of estrogen-positive and HER2-negative breast cancer." (PMID 32101536, 2020).
breast cancer (continued). "In the present study, we confirmed that compared with luminal or HER2-positive breast cancer cells, TNBC cells exhibited less sensitivity to CDK4/6 inhibition." (PMID 32934206, 2020). "The inactivation of PI3K/AKT signaling modulated by beta-naphthoflavone inhibited cyclinD1/D3 and cyclin-dependent kinase 4 (CDK4), resulted in cell cycle arrest in breast cancer cells." (PMID 31968672, 2020). "To test the generality of the synergy, we knocked down CDK1/CDK4/CDK6 in cell lines derived from different cancer types, including A549 (non-small cell lung cancer) and MCF7 (ER+ breast cancer), and treated them with metformin." (PMID 32811807, 2020). "Current treatment options for HR+, HER2‐negative advanced breast cancer (ABC) include endocrine therapies (eg, tamoxifen and aromatase inhibitors), targeted therapies (eg, cyclin‐dependent kinase 4/6 [CDK4/6] inhibitors), and chemotherapy." (PMID 32697890, 2020). "Triple combination therapy against PI3K:CDK4/6:ER prevented and/or delayed the onset of resistance in treatment-naive ER+/HER2− breast cancer models." (PMID 32795346, 2020). "mTOR activity can also be stimulated, independently of the PI3K pathway, by CDK4 and PIM kinases, both of which have been identified as potential mechanisms of resistance to PI3K inhibitors in breast cancer." (PMID 32391118, 2020). "To further examine the pathological correlations between p-USP51, ZEB1, and CDK4/6 activity, we performed immunohistochemical staining for p-RB, p-USP51, and ZEB1 in 265 cases of human primary breast carcinoma." (PMID 32296027, 2020). "According to the clinical data from the use of CDK4/6 inhibitors in breast cancer, there have been significant improvements in the median PFS in breast cancer patients." (PMID 30959874, 2019). "Here, the authors show that FGFR1 amplification is a resistance mechanism to CDK4/6 inhibitor and endocrine therapy and that combined treatment with FGFR, CDK4/6, and anti-estrogens is a potential therapeutic strategy in Era+ breast cancer tumors." (PMID 30914635, 2019). "A clinical trial is in place targeting CDK4/6 (SHR6390) and HER2 (Pyrotinib) in advanced breast cancer (NCT03993964)." (PMID 31681564, 2019). "Strikingly, the combined targeting of CDK4/6 and HER2 using abemaciclib and trastuzumab in patient-derived xenograft (PDX) models of treatment-refractory HER2-positive breast cancer displayed enhanced anti-tumor activity in vivo." (PMID 30959874, 2019). "For patients with HR+/HER2- advanced breast cancer whose disease progressed on one or more lines of treatment, several studies demonstrated a PFS benefit for CDK4/6 inhibitors plus endocrine therapy." (PMID 31695840, 2019). "CDK4/6 inhibitors are ATP-competitive inhibitors of cyclin-dependent kinases CDK4 and CDK6 that have shown efficacy for treatment of patients with hormone receptor (HR)+/HER2- advanced breast cancer." (PMID 31695840, 2019). "mTOR is targeted by everolimus (along other small molecules; approved by FDA in breast cancer treatment) and is also one of the few intracellular proteins targeted by FDA-approved small molecule drugs (along with CDK4/CDK6 and PARP enzyme)." (PMID 31681603, 2019). "The addition of targeted agents, everolimus, or CDK4/6 inhibitors to endocrine therapy has considerably improved the outcomes of patients with metastatic HR-positive, HER2-negative breast cancer." (PMID 31065872, 2019). "Accumulating evidence indicates that enhanced activation of oncogenic molecular signaling pathways such CDK4/6, HDAC, Src, IGFR-1, FGFR and PI3K/Akt in breast cancer cells plays a significant role in developing therapy resistance." (PMID 31660072, 2019). "On the basis of its good performance in clinical trials, the specific CDK4/6 inhibitor palbociclib has been approved by the FDA and EMA for HR-positive and HER2-negative advanced breast cancer." (PMID 31652270, 2019). "The benefit of combined CDK4/6 and anti-HER2 therapy in breast cancer is limited due to acquired resistance." (PMID 31444334, 2019).